IGF1R (insulin like growth factor 1 receptor)
Diseases named in the same sentence as IGF1R in open-access papers (continued):
Sharing a sentence is not in itself a finding about the gene and the disease.
tumor (continued). "In this research, we started to delineate a possible mechanism for the antitumor effect of calorie restriction (CR → increases mirR-15b → reduces IGF1R → reduced tumor growth)." (PMID 37686596, 2023). "The IGF-1R, known to play an important role in regulating cell proliferation and tumor progression, has also been shown to form a complex with and be activated by sE-cad." (PMID 37760996, 2023). "It was demonstrated, for the first time, that the abundance of EGFR, INSR, VGFR3 and AXL, is lower in tumours relative to livers from healthy individuals whilst the opposite is true for IGF1R." (PMID 36890818, 2023). "All these trials have been unsuccessful, indicating that there are tumor-suppressive/antimetastatic functions of IGF1R." (PMID 37237509, 2023). "This study showed that the concomitant application of tumor-derived self DNA with IGF-1R inhibitors exhibited an anti-proliferative effect, which was counteracted by the simultaneous inhibition of TLR9 signaling." (PMID 36835075, 2023). "Slide-seqV2 analysis of the IGF1-IGF1R interaction confirmed the co-localization of tumor cells expressing IGF1R and fibroblasts expressing IGF1." (PMID 36750562, 2023). "Conversely, there is an interplay between CD44v6 and insulin-like growth factor 1 receptor (IGF-1R) that contributes to tumor cell homing and stimulates cell proliferation." (PMID 37491225, 2023). "The different activation of IGF-1R signaling and tumor formation is also highly correlated with the diversity of niches." (PMID 36835075, 2023). "miRNA-122 exerts its tumor suppressive effect by inhibiting cyclin G1, inhibiting the insulin-like growth factor 1 receptor pathway, inhibiting the expression of toll-like receptor 4 in tumor cells, etc.." (PMID 37546394, 2023). "PACT6 enhances IGF1R mRNA stability through the PACT6-IGF2BP2-IGF1R RNA–protein trimer, thereby upregulating IGF1R expression and promoting bone metastasis and tumor growth in PCa." (PMID 38117350, 2023). "Mir-203a-3p has been previously reported as a tumor suppressor gene targeting IGF-1R, thus this study further clarifies this relationship." (PMID 37573302, 2023). "IGF-1R can be rapidly phosphorylated after tumor irradiation, which promotes tumor recovery from radiation." (PMID 36831629, 2023). "Given that we measured increased tumoral expression of miR-15b in CR mice and the reduced tumor expression of Igf1r, we interrogated if upregulation of miR-15b affects the levels of IGF1R." (PMID 37686596, 2023). "Expression of IGF-1R, a transmembrane tyrosine kinase receptor of the insulin receptor family, is related to a malignant phenotype, tumor progression, chemoresistance, and unfavorable survival in CRC." (PMID 38001121, 2023). "We propose that PTEN mutation or inactivation is one means by which tumor cells become resistant to ER stress-induced apoptosis, resulting in increased ATF6 and enhanced Entpd5/IGF1R expression, promoting protein glycosylation and folding." (PMID 36824269, 2023). "HDAC4 and IGF1R had differentially hydroxymethylated CpGs and increased expression in oligodendrocyte precursor cells across all four of our tumor types." (PMID 36909536, 2023). "Both in vitro and in vivo experiments indicate that Dox-induced knockdown of NEDD4 significantly suppresses tumor growth of IGF1R-dependent GC cells and NEDD4 overexpression promotes tumor growth of IGF1R-dependent GC cells." (PMID 36774408, 2023). "Multiple agents targeting IGF-1/IGF-1R signaling have shown effects against tumor growth in tumor xenograft models, but further verification of their effectiveness in PCa patients in clinical trials is still needed." (PMID 36831629, 2023). "In fact, a decreased production of fibronectin, IGF1 and IGFBP2 by haploinsufficient IGF1R fibroblasts, together with a downregulation of integrins expression in tumour cells, impaired the survival of tumour cells." (PMID 37033265, 2023).
tumor (continued). "HER2 is also known to form heterodimers with other kinases, such as insulin-like growth factor 1 receptor (IGF-1R), particularly in trastuzumab-resistant tumor cells." (PMID 36291900, 2022). "The knockdown of the SNCG gene leads to the inhibition of IGF-1 and IGF-1R, and, consequently, cell proliferation and tumor growth." (PMID 35203638, 2022). "Even though both circ_0002137 and miR‐433‐3p have ability to inhibit the overexpression of IGF1R on tumour cells, circ_0002137 was more stabilized than miRNAs because of the special structure of circular RNAs." (PMID 33621401, 2022). "Our previous studies reported IGF1R expression levels in human tumors are inversely correlated with several key target genes that alter the tumor microenvironment." (PMID 36568144, 2022). "To explore the relationship between YAP/TAZ and total and nuclear phosphorylated IGF-1R (pIGF-1R), we evaluated sequential tumor sections from a 37-patient tissue microarray by confocal microscopy." (PMID 35284040, 2022). "Several types of antibodies, including mAbs, bispecific antibodies, and antibody fragments, against IGF-II have been reported 15-18, which markedly deactivate the IGF-1R/IR and affect tumor growth." (PMID 35399718, 2022). "IGF-1 interacts with its cognate receptor IGF1R on the surface of tumor cells to activate the phosphatidylinositol 3-kinase (PI3K) signaling pathway, subsequently resulting in tumor resistance and proliferation." (PMID 35600367, 2022). "Recent studies have shown that hsa-miR-1275 binds to the 3′UTR of IGF-1R and acts as oncogene to promote the occurrence and development of tumor." (PMID 35600587, 2022). "Given the significant roles of IGF1R in tumor development and progression, inhibition of IGF1R activity has been suggested as a therapeutic strategy for many malignancies." (PMID 35651701, 2022). "In the present study, we determined the effects of carbohydrates in the diet, glucose in the TME and the effects of IGF1R on tumor cell growth and progression." (PMID 35574343, 2022). "Insulin-like growth factor (IGF-1) is associated with several oncogenic processes in cells and the IGF-1 receptor (IGF-1R) is a pivotal receptor tyrosine kinase that regulates malignant tumor transformation of ES cells." (PMID 35454895, 2022). "The co-expression of P-cadherin and E-cadherin and a partial EMT phenotype in IGF1R-reduced Wnt1 tumors suggests increased metastatic properties of these tumor cells." (PMID 36568144, 2022). "Consistently, silencing IGF1R or PTK2 decreased tumor growth in the liver, the occurrence of pulmonary metastasis, and the number of pulmonary metastasis lesions, resulting in prolonged OS of nude mice bearing orthotopic xenografts of PLC/PRF/5-LV-BACH1 cells." (PMID 35154476, 2022). "Each dot on the IGF-1R expression plot represents one tumor (red) or normal (green) sample and the samples above the median (expression line) are considered to be overexpressed compared to their corresponding normal tissues." (PMID 36551732, 2022). "Intriguingly, IGF1R overexpression was observed in multiple kinds of tumour tissue, especially in OS patients." (PMID 33621401, 2022). "In ILC, both PAPPA and IGF1 were significantly upregulated in the stroma compared to the epithelium (p < 0.0001), while IGF1R was found predominantly in the tumor epithelium (p < 0.05)." (PMID 35205651, 2022).
tumor (continued). "qPCR results showed that Pappa, Igf1 and Stc1 were only expressed in the CAFs, while Igf1r, Stc2 and Igfbp4 were expressed in both tumor cells and CAFs." (PMID 35205651, 2022). "Our in vitro experiments specify the connection between IGF1R expression, tumor progression and the extracellular glucose level." (PMID 35574343, 2022). "Subsequently, the expression levels of LINC01291, miR-625-5p, and IGF-1R were measured in tumor xenografts." (PMID 33674778, 2022). "We further found that reduced IGF1R signaling in tumor epithelial cells dysregulates cadherin expression resulting in reduced cell adhesion." (PMID 36568144, 2022). "Here, we studied the implication of IGF1R as a cancer-promoting factor in the TME by analyzing tumor samples from NSCLC patients, and generating LLC models by performing heterotopic transplantation or pulmonary metastasis in the context of IGF1R deficiency." (PMID 35688943, 2022). "The concomitant use of tumor-derived self-DNA and IGF1R inhibitors displays anti-proliferative potential." (PMID 35651701, 2022). "Since dysregulation of the PI3K pathway results in tumor proliferation, all of these increased dependencies are consistent with a phenotype of oncogenic pathway addiction in the IGF1R/PI3K pathway." (PMID 35382456, 2022). "Insulin-Like Growth Factor 1 Receptor (IGF1R)—another member of the RTK family—can also be activated by LL-37 which is involved in signaling pathways related to tumor development." (PMID 36294968, 2022). "Our previous studies showed heightened cell stress driven by attenuated IGF1R resulted in immune cell evasion and a pro-metastatic tumor microenvironment." (PMID 36568144, 2022). "The impact of nuclear IGF1R on tumor aggressiveness can be deduced from the fact that inhibition of nuclear IGF1R import correlated with a reduced proliferative potential." (PMID 36479090, 2022). "For instance, linsitinib was reported to exert a superior anti-tumor activity of IGF-1R TKI and significantly blocked the compensatory INSR-A signaling." (PMID 36233084, 2022). "The tumor niche can provide a protective microenvironment, and therefore the simultaneous blocking of IGF-1R and SFKs signaling should be further investigated for T-ALL patients." (PMID 35217681, 2022). "Our study reveals that ABCA6 acts as tumor suppressor in EWS cells via cholesterol-mediated inhibition of IGF1R/AKT/MDM2 signaling, which promotes the pro-apoptotic effects of doxorubicin and reduces cell migration." (PMID 36149602, 2022). "Possible effects of the overexpression of ADAM12 are the upregulation of growth pathways through enhanced expression of a subset of EGFR ligands and increased IGF-1R signaling, which contribute to increased tumor proliferation and metastasis." (PMID 35413826, 2022). "In recurrent GBM, the phosphatidylinositol 3-kinase (PI3K) pathway activity, driven by macrophage-secreted insulin-like growth factor-1 (IGF-1) and tumor cell IGF-1 receptor (IGF-1R), was increased." (PMID 35967394, 2022). "Polypeptides from Arca subcrenata Lischke inhibited growth of HT-29 cells and suppressed tumor growth in male mouse xenograft by reducing IGF1R phosphorylation and inhibiting IGF-I/IGF1R signaling activation." (PMID 36013453, 2022). "We provide evidence that the protective role of FOXA1 on LUAD cells is highly dependent on induction of IGF2, which is a multifunctional growth factor that promotes tumor cell survival via activating IGF1R signaling cascade." (PMID 35974000, 2022). "IGF-1 plays a major role in tumor cell proliferation and survival, and its receptor, IGF-1R, plays a significant role in a multi-step process of cancer metastasis." (PMID 36551732, 2022). "In some tumours, IGF‐1R is redistributed in lipid rafts, thus activating downstream pathways and enhancing an antiapoptotic effect on tumour cells." (PMID 34939255, 2022).
tumor (continued). "After injection of dominant negative mutant IGF-1R, tumor cell apoptosis was initiated, cancer growth was inhibited, and the metastatic proliferation was decreased." (PMID 35158856, 2022). "Both elevated IGF1R and PTK2 expression were related to increased tumor number, tumor encapsulation loss, microvascular invasion, less differentiation, and poor TNM staging." (PMID 35154476, 2022). "let-7e is a tumor suppressor that is down-regulated—partially by the elevated expression of IGF1R—in CRC cells." (PMID 35627259, 2022). "We initially analyzed scRNA-seq of the whole tumor to profile changes in tumor cell populations when IGF1R is either reduced or attenuated in the tumor epithelium." (PMID 36568144, 2022). "Herein we report increased amplification and mRNA expression, as well as increased protein expression (IGF1R/p-IGF1R) and IGF1R levels in tumor samples and serum from NSCLC patients, respectively." (PMID 35688943, 2022). "By analyzing IGF1R expression depending on the tumor grading, we found elevated mRNA levels in patients with G2 grading." (PMID 35574343, 2022). "For example, IR-A and IGF-1R are abundantly expressed in the neural stem cells, and heterodimeric receptors formed by IR-A can maintain the renewal of tumor stem cells or neural stem cells." (PMID 36358907, 2022). "In recent years, relevant research has focused on the dynamic balance between IGF1R ubiquitination and deubiquitination with both performing key regulatory functions determining the survival or mortality of tumours." (PMID 36452079, 2022). "This small (7.5 kDa) tracer demonstrated a strong correlation between its uptake and the IGF-1R expression level in human tumor xenografts in mice." (PMID 35890370, 2022). "Of note, this is the first report showing that IGF1R acts in the lung TME sustaining inflammation and tumor-associated immunosuppression." (PMID 35688943, 2022). "Overexpression of IGF1R and PTK2 rescued the inhibition of tumor growth and metastasis caused by BACH1-depletion." (PMID 35154476, 2022). "Here, we noticed a correlation between IGF1R mRNA expression levels in the tumoral region and the BMI as well as with the tumor diameter, a marker for tumor development and growth." (PMID 35574343, 2022). "The worst overall survival was seen in patients whose tumor was CD44-high/IGF1R-high (n = 42, mean survival 22.8 months)." (PMID 35931675, 2022). "Accordingly, IGF1R deficiency decreased expression of p-IGF1R in blood vessels, fibroblasts, tumor-associated macrophages and FOXP3+ tumor-infiltrating lymphocytes." (PMID 35688943, 2022). "miR-223 significantly inhibits the proliferation, growth rate, and colony formation of cells in vitro, and tumor formation in vivo through targeting IGF-1R and its downstream PI3K/Akt/mTOR/p70S6K pathway in leukemia." (PMID 35205115, 2022). "Given its established roles in tumor development, progression and metastasis, IGF-1R is a promising drug target for combination therapy against CRC." (PMID 36497233, 2022). "In several tumor tissues, unbalanced IGF1R signaling can promote cancer cell proliferation and activate cancer reprogramming." (PMID 35651701, 2022). "Based on the tumor/normal fold change data, the gene IGF1R was found to be significant with a Kaplan–Meier p-value of 0.009." (PMID 35406404, 2022). "Using co-IF approaches, we further assessed the activation of IGF1R and Wnt/β-catenin axes in hARtg+ tumor cells." (PMID 35902588, 2022). "Conditional deletion of Igf1r significantly increased tumor latency in pregnant mice, reaffirming the status of IGF1R as an oncogene." (PMID 35784559, 2022). "Within the insulin/IGF axis, IGF-1R is capable of stimulating the proliferation and migration of tumor cells through binding with insulin and IGF-1 and activating the downstream tumor-promoting signal pathways." (PMID 35296101, 2022).
tumor (continued). "The MMTV-Wnt1/K8-CreERT/Igf1rfl/fl line allows for investigation into the role of IGF1R specifically in the luminal lineage and to determine its effect on tumor phenotype." (PMID 35784559, 2022). "The pharmacological inhibition of IGF-1-R led to induction of apoptosis, inhibition of growth and subsequent tumor size reduction." (PMID 36357661, 2022). "Although our in vivo results revealed that HBMSCs with overexpression of miR-99b-5p obviously inhibited tumor growth and downregulating the expression of IGF1R, the manipulation of IGF1R in vivo should also be explored to confirm the conclusion." (PMID 35030978, 2022). "Similar to the dnIGF1R expressing Wnt tumors, luminal specific deletion of IGF1R resulted in lower tumor latency and increased metastasis compared to control animals." (PMID 35784559, 2022). "We found a direct correlation between the BMI as well as the tumor diameter and IGF1R mRNA expression level." (PMID 35574343, 2022). "Of particular interest for the development of therapeutic strategies for preventing tumor relapse, blockade of IGF-1R with small molecules disrupted vascular reconstruction and delayed tumor relapse." (PMID 36017326, 2022). "In conclusion, we demonstrated that IGF1R mRNA expression level directly correlates with the BMI and tumor diameter of patients with LUAD." (PMID 35574343, 2022). "The staining intensity of IGF-1R protein was assessed in tumor and margin tissues and the results are presented as the percentage of positive reactivity." (PMID 36713521, 2022). "We analyzed 31 unique tumor types and their corresponding normal tissues, including UM tumors from The Cancer Genome Atlas (TCGA) data for IGF-1R gene expression." (PMID 36551732, 2022). "The overexpression of IGF-1 and IGF-1R has been observed in many tumor cell lines and tissues, and their overexpression is closely related to the poor prognosis of patients." (PMID 36142299, 2022). "Metformin can stop the feedback regulation of the IGF-1R signaling pathway and synergistically kill tumor cells when combined with IGF-1R inhibitors." (PMID 36397350, 2022). "To test the functional role of altered E-cadherin and P-cadherin in cells with attenuated IGF1R, we first transiently re-expressed E-cadherin in DN-Wnt1 primary tumor epithelial cells and measured cell adhesion in vitro." (PMID 36568144, 2022). "The high proliferation phenotype allowed the authors to culture primary cells and create xenograft models to determine the efficacy of IGF1R inhibitors on tumor cell growth." (PMID 35784559, 2022). "Reduced IGF1R by function or expression results in increased tumor metastasis in the mouse models and aligns with human survival data indicating an inverse relationship between IGF1R expression and overall patient survival." (PMID 36568144, 2022). "Seven days were required to reach a tumor-to-blood ratio of 8.1 ± 2.5 for tumors with a high expression level of IGF-1R." (PMID 35890370, 2022). "On the other hand, p-ERK1/2 is a major IGF1R MAP kinase signaling mediator that was extensively reported to be activated in NSCLC and associated with tumor cell proliferation." (PMID 35688943, 2022). "As regulators of IGF signaling through IGF1R, IGFBPs were originally regarded as having a predominantly tumor suppressive role." (PMID 35597813, 2022). "Our data show that SSO55 can effectively shift the splicing of IR to IR-B isoform and consequently decrease angiogenesis in grafted tumor cells in the presence of IGF-1R antibodies." (PMID 35017650, 2022). "We further show that reduced IGF1R signaling in tumor epithelial cells dysregulates E- and P-cadherin resulting in reduced cell adhesion." (PMID 36568144, 2022). "Data on the FGF2, FGFBP1, TGFA, TGFBR3, and IGF1R expression levels were analyzed using TIMER 2.0 that matched TCGA tumor tissue with normal tissue." (PMID 36430763, 2022). "IGF-1R is recognized to play a key role in tumorigenesis, and protection of tumor cells from apoptosis triggered by chemotherapy." (PMID 36361620, 2022).